MTOR (mechanistic target of rapamycin kinase)
Diseases named in the same sentence as MTOR in open-access papers (continued):
Sharing a sentence is not in itself a finding about the gene and the disease.
tumor (continued). "Overexpression of mTOR gene is the cause of a wide range of tumours that leads to end-stage renal disease by kidney involvement." (PMID 23401839, 2013). "In a xenograft model, temsirolimus suppressed the growth of PC-9 cells overexpressing the HGF-gene; this was associated with suppression of the mTOR signaling pathway and tumor angiogenesis." (PMID 23690929, 2013). "Studies in cultured cells have confirmed that S6K activity is enhanced by mechanisms activating the PI3-kinase/Akt/mTOR pathway, such as loss of the tumour suppressor PTEN, and have shown a positive correlation between S6K activity and tumour growth." (PMID 24072592, 2013). "Many of the major elements of the PI3K/AKT/mTOR pathway have been found mutated or amplified in a wide variety of tumor types and for this reason PI3K inhibitors have been sought after." (PMID 23935891, 2013). "Only the combination of AEE788 with dovitinib caused a significant block in the PI3K/Akt/mTOR pathway and resulted in strong anti-tumor activity." (PMID 23343422, 2013). "An impact of Pten status on sensitivity to mTOR inhibitors has been observed in PTEN-deficient tumour cells and Pten-deficient MEFs, which were both more sensitive to mTOR inhibitors than corresponding Pten positive cells." (PMID 23139750, 2012). "There are examples demonstrating the ability of several mutated receptor tyrosine kinases, as well as tumor suppressor loss, to converge on the mTOR pathway to enhance gliomagenesis in vivo." (PMID 23077666, 2012). "Activated Akt causes tumor cell survival and inhibits of apoptosis by phosphorylating numerous downstream targets including mTOR and GSK3β." (PMID 22899960, 2012). "There are studies correlating the activation of mTOR with tumor progression and metastatic potential in KRAS-mutated NSCLC models." (PMID 24281308, 2012). "The Salvador-Warts-Hippo (SWH) tumor suppressor and the mammalian target of rapamycin (mTOR) pathways have been implicated as key regulators of both cell proliferation and apoptosis." (PMID 24710534, 2012). "Overexpression of mTOR is reportedly associated with tumor grade, ALI, TNM stage, high Ki-67 labeling, and other poor prognostic features in HCC." (PMID 23162604, 2012). "Activating mutations in kinases involved in signalling via the PI3K/mTOR/S6K pathway were identified in many tumours indicating the oncogenic nature of this signalling pathway." (PMID 22570651, 2012). "To further investigate the role of OGT in regulating sensitivity to inhibitors of the PI3K pathway, we next analyzed the effects that the loss of OGT expression had on tumor cell line sensitivity to the dual PI3K/mTOR inhibitor, NVP-BEZ235." (PMID 23029544, 2012). "Rheb-GTP/mTOR signaling has been implicated in tumor development, via its downstream modulation of protein synthesis, cell proliferation, cell cycle progression, and cell survival." (PMID 23202921, 2012). "To further reveal mechanisms underlying this tumor suppressive effect of miR-99a, we knockdowned mTOR in RCC cells." (PMID 23173671, 2012). "Tir8/Sigirr-deficiency was associated with increased Akt-mTOR signaling and tumor initiation through its impact on cell proliferation and LOH of Apc in epithelium." (PMID 23112799, 2012). "In summary, we demonstrated that PI3K/mTOR dual inhibitors are effective radiosensitisers in tumor cells with EGFR overexpression or oncogenic Ras mutation." (PMID 22452803, 2012). "mTOR overexpression was detected in 23% (33/142) of the tumours, predominantly with high nuclear grade tumours (P=0.034), and in association with α-IGF1R (47% P<0.000), p110α (64% P=0.028) and pBad (65% P=0.027)." (PMID 22454081, 2012). "Since the mTOR pathway is already activated in NF1-associated tumours due to a lack of NF1, it is likely that further activation of the Akt/mTOR pathway due to Pten loss promotes tumour progression in this setting." (PMID 23139750, 2012).
tumor (continued). "In a number of in vitro cell-lines and in vivo murine xenograft models, aberrant mTOR pathway activation through oncogene stimulation or loss of tumour suppressors contributes to tumour growth, angiogenesis and metastasis." (PMID 22408430, 2012). "Multivariate analysis also revealed that several alterations in the mTOR pathway tended to be associated with reduced tumor-free survival (HR: 2.9; P = 0.06)." (PMID 22779004, 2012). "The formation of a multi-molecular complex between mTOR and regulatory-associated protein of mTOR (raptor) has a role in cell proliferation, survival and tumour angiogenesis." (PMID 21285971, 2011). "A variety of transformed or tumour cells with deregulated mTOR signalling have shown higher susceptibility to inhibitors of mTOR than normal cells." (PMID 21904669, 2011). "mTOR signalling has been described as implicated in tumour development, metastasis, and drug resistance; thus, mTOR targeting successfully inhibits tumour growth and renders them sensitive to conventional treatments." (PMID 21437224, 2011). "PTEN silencing or inactivating mutations have been detected in a wide variety of human neoplasias (including prostatic and endometrium carcinomas, glioblastomas, melanoma, and T-cell acute lymphoblastic leukemia) and this results in Akt/mTOR up-regulation." (PMID 20671809, 2010). "The synthetic lethality relationship between PTEN deficiency and mTOR-overexpression inhibition was discovered by showing an enhanced sensitivity of PTEN-deficient tumours to the mTOR inhibitor CCI-779, a rapamycin homologue." (PMID 19319136, 2009). "mTOR activation leads to increased synthesis of multiple proteins, including several that have been implicated in the pathogenesis of multiple tumor types." (PMID 19860903, 2009). "Of the other AKT/mTOR components evaluated only pS6 demonstrated a significant association with tumour grade (P=0.008)." (PMID 18283322, 2008). "Nevertheless, the composite covariates of caveolin-1 and activated AKT/mTOR components serve as linked molecular signatures that clearly identify localised tumours, which have high invasive capacity and an increased metastatic potential." (PMID 18283322, 2008). "In a follow-up prospective phase I study of patients with molecularly defined PTEN deficient GBM tumours, the MTOR inhibitor rapamycin was shown to cross the blood--brain barrier." (PMID 22275966, 2008). "The mTOR pathway is also important in oncogenesis as PTEN, a tumor suppressor that functions upstream of mTOR, is mutated in many brain, prostate and other tumors." (PMID 17986349, 2007). "Hypoxia and HIF-1α are known to be linked to mTOR signaling, so this observed signaling dichotomy may be coordinated by hypoxia and is indicative of multiple tumor cell states." (PMID 41568176, 2026). "Ex vivo drug testing revealed a striking response: the mTOR inhibitor Sapanisertib induced extensive tumor necrosis and was associated with near-complete depletion of ALDH1A1+ and NTN4+ states, accompanied by strong stress/apoptosis signatures and reduced endothelial cells." (PMID 42070010, 2026). "In addition, the PI3K/AKT/mTOR signaling pathway is critical for maintaining the survival of tumor stem cells and causing tumor evasion." (PMID 40863244, 2025). "Similarly, mitochondrial sirtuins, especially SIRT3, interact with mTOR regulators and inhibit tumour progression, also sensing the nutrient deficiency via NAD+ and activating the AMPK pathway to restore balance." (PMID 40908838, 2025). "The findings suggested that RTN4 might be implicated in the PI3K_AKT_mTOR pathway, cellular responses to hypoxia and inflammatory responses in the genesis and progression of tumours." (PMID 39969103, 2025). "Furthermore, mutations activating the PI3K/Akt/mTOR pathway are known to increase glycolysis in tumor cells and impair effector T-cell function by depleting environmental glucose." (PMID 40504311, 2025).
tumor (continued). "We next evaluated downstream markers associated with mTOR signaling in tumor tissue." (PMID 41436543, 2025). "Ipatasertib was selective for tumor cells harboring activating PI3K/AKT/mTOR pathway mutations." (PMID 40761343, 2025). "Given that these proteins physically interact in cells, their consistent co‐expression across tumor types may reflect an underlying regulatory coordination, potentially related to mTOR pathway modulation." (PMID 40653822, 2025). "This indicates that MARK3 overexpression may inhibit the activation of the PI3K/AKT/mTOR signaling pathway, which is associated with cell survival, tumor progression, and resistance to therapeutic interventions." (PMID 40136361, 2025). "Furthermore, transcription factors are responsible for the mediation of the mTOR signalling pathway, causing gene expression reprogramming, which ultimately promotes the growth of tumour as well as its survival." (PMID 40407951, 2025). "Additionally, mTOR inhibition reduces the activity of pathways linked to angiogenesis and inflammation, both of which are critical for tumor growth and progression." (PMID 39940361, 2025). "Additionally, mutations in PIK3CA (encoding the catalytic subunit of PI3K) and loss of PTEN (a tumor suppressor that negatively regulates PI3K signaling) lead to hyperactivation of the PI3K/AKT/mTOR pathway." (PMID 40427153, 2025). "Moreover, HER2 amplification has been implicated in the activation of the PI3K/AKT/mTOR axis, promoting tumor proliferation and resistance to chemotherapy." (PMID 39953539, 2025). "These mutations activate the PI3K/AKT/mTOR pathway, contributing to tumor growth and survival." (PMID 41425867, 2025). "For example, in EGFR-mutant lung adenocarcinoma cells, metformin inhibits mitochondrial electron transport complex 1 to induce AMPK activation, leading to the inhibition of the mTOR pathway, which causes G0/G1 cell cycle arrest, mitochondrial apoptosis, and reduction of tumor growth." (PMID 40983975, 2025). "This is particularly relevant for therapy, as activation of the PI3K/AKT/mTOR signaling has been associated with secondary IM resistance in GISTs; IM itself has been shown to induce autophagy as a survival strategy in quiescent tumor cells." (PMID 41168571, 2025). "mTOR signaling, in particular, has been linked to tumor growth and may serve as a therapeutic target, although clinical effectiveness has varied." (PMID 40182390, 2025). "EC exhibits the highest frequency of mutations in the PI3K/AKT/mTOR pathway compared to other tumor types in TCGA, suggesting that inhibitors targeting this pathway may benefit EC patients." (PMID 40391161, 2025). "Dysfunction or deletion of tumor suppressor phosphatase and tensin homolog (PTEN) can increase the incidence of deleterious mutations and activate AKT/mTOR signaling, thereby inhibiting autophagic death of tumor cells and promoting their proliferation and survival." (PMID 40066330, 2025). "Notably, TSC1 and TSC2 emerge as the most frequently mutated genes linked to activated mTOR signaling in HCC tumor samples." (PMID 39863613, 2025). "We therefore asked whether Pten loss (increased mTOR signaling) rescues the post-mitotic tumor cells from death by staining for SYP or NeuN and TUNEL." (PMID 40766638, 2025). "This enhanced neuronal activity is associated with metabolic alterations and activation of the mTOR signaling pathway, suggesting that D-2HG contributes to seizure onset and may be related to less aggressive tumor behavior and improved survival." (PMID 41541926, 2025). "Similarly, mutations in the PTEN tumor suppressor gene disrupt the phosphatidylinositol 3-kinase/protein kinase B/mechanistic target of rapamycin (PI3K/AKT/mTOR) signaling pathway, yielding a highly immunosuppressive microenvironment." (PMID 41281945, 2025).
tumor (continued). "Sirolimus, a mammalian target of rapamycin (mTOR) inhibitor, is currently primarily used in recipients with renal dysfunction post-LT, intolerable adverse reactions to calcineurin inhibitors (CNIs), and a risk of tumor recurrence." (PMID 40046750, 2025). "In OSCC, mTOR is frequently hyperactivated due to mutations or dysregulation of upstream signaling pathways, leading to autophagy inhibition and promoting uncontrolled tumor growth." (PMID 39840028, 2024). "Additionally, CoM tend to have a low presence of the tumor suppressor PTEN in their nuclear fraction and the PTEN tumor suppressor’s loss of function can also trigger activation within PI3K/AKT/mTOR cell proliferation pathway." (PMID 39055896, 2024). "Furthermore, in murine tumor models undergoing radiotherapy, mTOR inhibitors delay tumor progression associated with FBXW7 mutations or deletions." (PMID 39749199, 2024). "Additionally, glutamine metabolism is intricately linked to the mTOR signaling pathway, which is crucial for tumor cell proliferation and growth." (PMID 39669498, 2024). "Furthermore, VHL inactivation also leads to the overactivation of the mTOR, which is associated with tumor progression and a poorer prognosis in ccRCC." (PMID 39092291, 2024). "Additionally, wildtype RHEB, wildtype mTOR, and another tumour-associated mutant, mTORR2505P induced pT401, albeit to a lesser extent." (PMID 39223665, 2024). "Therefore, abnormal mTOR activation via loss of functional Tsc1 or Tsc2 promotes oncogenesis by maintaining the necessary cellular signals for tumor growth, survival, and proliferation." (PMID 39352796, 2024). "The regulation of energy metabolism in tumor cells is influenced not only by glycolysis but also by metabolic alterations associated with glucose synthesis, which can result from mutations in oncogenes such as mTOR, AMPK, and KRAS." (PMID 39595613, 2024). "Since mTOR has been linked to reprogramming tumor metabolism and increasing levels of hypoxia-inducible factor 1 α (HIF-1α), we hypothesized that LMP2A would increase HIF-1α levels to enhance ATP generation in B lymphoma cell lines." (PMID 38612754, 2024). "Similarly, MTOR mutations can serve as biomarkers for predicting tumor responses to mTOR inhibitors, which are already being used to treat human cancer." (PMID 38491101, 2024). "However, the p.Asp409Asn mutation in PPP4R3A not only eliminates its tumor-suppressive function but also promotes the activation of the Akt-mTOR-S6K/4E-BP pathway, thereby enhancing cell proliferation." (PMID 38275415, 2024). "A recent study showed that mutations in USP9X increase sensitivity to mTOR inhibition, suggesting that mTOR inhibitors may represent a therapeutic approach for tumours harbouring USP9X mutations." (PMID 38785992, 2024). "Experimental data demonstrate that Tax induces the activation of the PI3K-Akt-mTOR (mechanistic target of rapamycin kinase) pathway by causing the mislocalization of the tumor suppressors PTEN and PHLPP (PH domain and leucine-rich repeat protein phosphatase) from the plasma membrane." (PMID 38276160, 2024). "However, overexpression of the PPP4R3A Asp409Asn mutant resulted in loss of tumor-suppressive function, ineffective inhibition of cell invasion, and even promotion of cell proliferation and migration by activating the Akt/mTOR signaling pathway." (PMID 38275415, 2024). "Furthermore, under hypoxic conditions, tumor-associated macrophages (TAMs) exhibit increased expression of the mTOR negative regulator REDD1, leading to reduced glycolytic activity." (PMID 39003350, 2024).
tumor (continued). "More recently, the mTOR/AKT pathway was implicated in the regulation of NDRG1 as a tumor/metastasis promoter, and TGFβ has also been found to be responsible for NDRG1 having tumor-promoting activity via regulation of the epithelial–mesenchymal transition, metastasis, and cancer stem cells." (PMID 38611020, 2024). "Mutations in TSC1/TSC2 can lead to mTOR overactivation, promoting tumor growth." (PMID 38731914, 2024). "Therefore, dual PI3K/mTOR have been associated with higher anti-tumor activity, but, unfortunately, also a higher toxicity profile." (PMID 36901954, 2023). "Among these molecular targets, the phosphatidylinositol 3-kinase (PI3K)/Akt/mammalian target of rapamycin inhibitor (mTOR) pathway has proved to be an indispensable driving signaling and associated with tumor progression, treatment response, and clinical outcomes in many types of tumors." (PMID 38093375, 2023). "Mutated EGFR reprograms the metabolism of tumor cells through the PI3K/AKT/mTOR pathway." (PMID 36994237, 2023). "EGFR signaling, which involves the mTOR pathway, is expressed in these tumors, and it is associated with tumor proliferation, invasive behavior, lower total resection, and epithelial-to-mesenchymal transition; this latter is also mediated by the ADAM12 metalloprotease." (PMID 37958702, 2023). "They observed a specific trend in TSC/MTOR mutation in different tumours." (PMID 36816543, 2023). "Similarly, GSH-deficient regulatory T cells display increased serine synthesis, mTOR activation, and proliferation, which is linked to both autoimmunity and increased tumor rejection in vivo." (PMID 37187454, 2023). "Additionally, mTOR activation is associated with tumor development and plays an important role in maintaining the stemness of CSCs." (PMID 36816969, 2023). "Treatment of mutationally activated PI3K alpha in HCT116 and NCI-H460 tumor cells with PWT33597 showed that this drug could inhibit mTOR pathway proteins and PI3K." (PMID 37046703, 2023). "Further, a positive feedback loop between TCTP and mTOR contributed to neurofibromatosis type 1 (NF1)-associated tumor, and rapamycin was effective in down-regulating TCTP expression, suggesting that the TCTP protein level was controlled by mTOR-dependent translational regulation." (PMID 37842235, 2023). "The PI3K/AKT/mTOR signaling pathway plays a crucial role in regulating various cellular processes, including proliferation, transcription, translation, apoptosis, and angiogenesis, and is associated with mammalian tumor immunity." (PMID 37152048, 2023). "The inhibition of the MEK1/2-ERK signaling axis is also shown to activate the PI3K/AKT/mTOR pathway in tumor cells and macrophages, which could have caused changes in the metabolic processes." (PMID 37833877, 2023). "MTOR is associated with the anti-tumor mechanism of ALK inhibitors." (PMID 37906510, 2023). "Activation of the PI3K‐AKT‐mTOR pathway in tumours is due to point mutations or amplifications of kinases (PIK3CA, AKT and MTOR), upstream receptor tyrosine kinases (epidermal growth factor receptor [EGFR], HER2, MET and FGFR) or small GTPases of the RAS family (HRAS, KRAS and NRAS)." (PMID 37877351, 2023). "Our study demonstrates that S100a9 may inhibit MDS-associated tumor escape via PD-1/PD-L1 blockade through PI3K/AKT/mTOR signaling pathway activation." (PMID 36810783, 2023). "We also confirm that the mTOR pathway is strongly implicated in the pathogenesis of this tumor mainly through MTOR, TCS1, and TSC2 mutations, but other genes could also be involved in the pathway activation, especially in LOTs without “canonical” mutations." (PMID 37845471, 2023). "In addition, these articles underline the fact that the PI3K/AKT, MAPK/ERK, and/or mTOR signaling pathways play a crucial role, via their activation or inhibition, in the pro- or anti-tumor role played by the PD-1 inhibition/blockade." (PMID 37370798, 2023).